ZNF736 (zinc finger protein 736)
Description:
May be involved in transcriptional regulation.
Tractability: PROTAC: ubiquitination databases record sites on it.
Gene: Protein-coding gene on chromosome 7 (64,307,459 to 64,356,634, forward strand). Ensembl gene ENSG00000234444.
Subcellular location: Nucleus
Subcellular location (Human Protein Atlas): Nucleoplasm
Pathways (Reactome):
Gene expression (Transcription): Generic Transcription Pathway
Gene Ontology:
Molecular function: DNA-binding transcription factor activity, RNA polymerase II-specific; RNA polymerase II cis-regulatory region sequence-specific DNA binding
Biological process: regulation of DNA-templated transcription; negative regulation of transcription by RNA polymerase II
Cellular component: nucleus
Genetic constraint (gnomAD): Loss-of-function variants: 7 observed, 10.78 expected, observed/expected ratio (o/e) 0.65, 90% interval 0.37 to 1.22. The upper end of that interval is the gene's LOEUF score, 1.22, which puts it in group 5 of 6, group 1 being the genes least tolerant of losing a copy. Missense variants: 444 observed, 482.68 expected, observed/expected ratio (o/e) 0.92, 90% interval 0.85 to 1. Synonymous variants: 139 observed, 161.09 expected, observed/expected ratio (o/e) 0.86, 90% interval 0.75 to 0.99.
Homologues: Orthologues: chimpanzee ZNF736 (99% identical), macaque ZNF736 (95% identical), mouse Zfp738 (52% identical), mouse Zfp457 (49% identical), mouse Zfp595 (49% identical), rat AABR07009105.1 (46% identical), mouse Zfp953 (35% identical). Paralogues in human: ZNF727 (82% identical), ZNF682 (62% identical), ZNF724 (60% identical), ZNF681 (59% identical), ZNF732 (59% identical), ZNF254 (59% identical), ZNF595 (58% identical), ZNF708 (58% identical), ZNF726 (58% identical), ZNF728 (58% identical), ZNF85 (57% identical), ZNF43 (57% identical), and 164 more.